SLC27A1 (solute carrier family 27 member 1)
Diseases named in the same sentence as SLC27A1 in open-access papers (continued):
Sharing a sentence is not in itself a finding about the gene and the disease.
cancer (30 papers, 2017 to 2025). A tumor composed of atypical neoplastic, often pleomorphic cells that invade other tissues. "In BCCMDA-MB-231 exposed to cancer-associated fibroblasts (CAF), FASN activity is decreased, FABP2 and FABP3 transcriptional expression are decreased, while FATP1/SLC27A1 transcriptional expression is increased." (PMID 40256431, 2025). "Looking at two different subtypes of grade 3 BCs: TNBC (N = 26) and luminal A (N = 36), with respectively high and low levels of FATP1/SLC27A1; the OS was significantly lower in patients with carcinomas with high levels of FATP1/SLC27A1." (PMID 31575907, 2019). "Since the results suggested that FA and estradiol, via ER-β, are relevant in the regulation of FATP1/SLC27A1 and since this gene is upregulated in high grade BCs, mainly TNBC, we hypothesized that the pharmacological inhibition of FATP1 might be a strategy to fight cancer." (PMID 31575907, 2019). "On the other hand, oleic acid (C18:1), which has antitumor effects in several types of cancers, is a preferred substrate of SLC27A1 and SLC27A6, but not SLC27A4." (PMID 36005596, 2022).
tumor (26 papers, 2016 to 2025). "For example, a positive correlation was found between SLC27A3 in the enhancing tumor region and SLC27A1 in the tumor core, and between SLC27A4 in the peritumoral area and SLC27A6 in the tumor core." (PMID 37239243, 2023). "Negative correlations were observed between SLC27A3 and SLC27A4 in the enhancing tumor region and between SLC27A1 and SLC27A5 in the tumor core." (PMID 37239243, 2023). "In this study, a positive correlation was found between BMI and SLC27A1 expression in the enhancing tumor region of glioblastoma tumors in men, which is inconsistent with the cited study that examined expression in muscle tissue." (PMID 37239243, 2023). "Specifically, a negative correlation was found between the peritumoral area and the tumor core for SLC27A1, suggesting differences in fatty acid metabolism between these two regions." (PMID 37239243, 2023). "In agreement, we noted a high proportion of tumor-specific positive SLC27A1 staining in gallbladder and pancreatic SCCs (Kruskal–Wallis test, p < 0.0001)." (PMID 35851595, 2022). "Furthermore, a negative correlation was found between the expression of SLC27A1 in the enhancing tumor region and a positive correlation between SLC27A1 in the enhancing tumor region and patient weight." (PMID 37239243, 2023). "Additionally, a positive correlation was observed between the expression of SLC27A1 in the tumor core and patient weight." (PMID 37239243, 2023). "Meanwhile, by analyzing the expression changes of 8 MMRGs between high-risk and high-risk groups, we know that SLC27A1, GPAT4, and TNFAIP8L3 were highly expressed in the prognosis of high-risk patients, which may be tumor promoting factors for OvCa." (PMID 37256178, 2023). "The three remaining genes represented two solute carrier transporters (SLC27A1 and SLC7A5) for amino acids and fatty acids and one membrane bound protease (ANPEP) that plays a role in tumour invasion and metastasis." (PMID 37495601, 2023). "In men, a positive correlation was observed between the expression of ELOVL1 and SLC27A1, and SLC27A3 in the tumor core." (PMID 37239243, 2023). "The expression levels of ANGPTL4 and PPARD were notably higher in tumour tissue, whereas the expression levels of FABP1, SLC27A1 and OLR1 were elevated in normal tissue." (PMID 37556076, 2023). "The results showed that SLC27A1 and SLC27A3 were higher-expressed in tumor samples of both sets, while SLC27A2, SLC27A4, and SLC27A5 expressions were much lower." (PMID 35927229, 2022). "Despite being not significant, a trend in decreased OS was observed with high FATP1/SLC27A1 expression and increased tumor grade." (PMID 31575907, 2019). "In women, there was a negative correlation between the expression of SLC27A1 and weight and BMI in the enhancing tumor region and a positive correlation with weight in the tumor core." (PMID 37239243, 2023). "A negative correlation of SLC27A1 expression was observed between the tumor core and the peritumoral area." (PMID 37239243, 2023). "In the tumor core, but not in the enhancing tumor region, there was a positive correlation between the expression of SLC27A1 and SLC27A4, both of which are involved in fatty acid uptake through the BBB." (PMID 37239243, 2023). "A positive correlation was observed between the expression of SLC27A1 and SLC27A3 in the enhancing tumor region, while a negative correlation was found with the expression of SLC27A4, SLC27A5, and SLC27A6." (PMID 37239243, 2023). "Specifically, a positive correlation was found between SLC27A1 and SLC27A4 with age in the tumor core, while a negative correlation was found with SLC27A5." (PMID 37239243, 2023).
tumor (continued). "In the tumor core of women, there was a negative correlation between the expression of SLC27A5 and a positive correlation between the expression of SLC27A4 and SLC27A1 with age." (PMID 37239243, 2023). "Women also showed a negative correlation between the expression of SLC27A1 in the peritumoral area and the expression of SLC27A3 in the tumor core." (PMID 37239243, 2023). "A negative correlation was found between SLC27A1 in the peritumoral area and SLC27A6 in the tumor core, between SLC27A3 in the enhancing tumor region and SLC27A5 and SLC27A6 in the tumor core, and between SLC27A3 in the tumor core and SLC27A5 in the peritumoral area." (PMID 37239243, 2023).
infection (4 papers, 2021 to 2025). The state of being infected such as from the introduction of a foreign agent such as serum, vaccine, antigenic substance or organism. "(A) Seahorse flux analyses of scramble or Plin2-/-, Slc27a1-/-, and Cpt2-/- macrophages infected with Mtb Erdman strain at a multiplicity of infection (MOI) of 1 24 hours post infection." (PMID 40080408, 2025). "Indeed, 4 hours post infection, IL-1β and IFN-β were both upregulated in Slc27a1-/- macrophages compared to scrambled controls consistent with their pro-inflammatory phenotype." (PMID 40080408, 2025).
SLC27A1 also shares sentences with these, for which no sentence is quoted: Hepatic steatosis (7 papers); metabolic syndrome (5); type 2 diabetes (4); B-cell lymphoma (3); metabolic disease (3); atherosclerosis (2); colorectal cancer (2); gestational diabetes (2); hepatoma (2); lung carcinoma (2); ovarian carcinoma (2); retinal degeneration (2); breast tumors (1); Cachexia (1); chronic kidney disease (1); Cognitive impairment (1); dermopathy (1); diabetic cardiomyopathy (1); facial paralysis (1); hyperlipidemia (1); immune diseases (1); intrahepatic cholangiocarcinoma (1); invasive carcinoma (1); liver cancer (1); metastatic cancer (1); metastatic melanoma (1); myocardial hypertrophy (1); myocardial ischemia (1); neurological disorders (1); non-alcoholic fatty liver disease (1).
A further 7 diseases each share a sentence with SLC27A1 in 1 paper.